CLPB (ClpB family mitochondrial disaggregase)
Diseases named in the same sentence as CLPB in open-access papers (continued):
Sharing a sentence is not in itself a finding about the gene and the disease.
leptospirosis (4 papers, 2018 to 2021). A contagious bacterial infection caused by spirochetes of the genus Leptospira. "A large number of publications also indicate that ClpB supports the virulence of bacteria, including a pathogenic spirochaete Leptospira interrogans responsible for leptospirosis in both animals and humans." (PMID 29670056, 2018). "Moreover, it has been shown that the ClpB deficiency made that pathogen avirulent in an animal model of acute leptospirosis (in gerbils), as compared to its parental strain." (PMID 34070174, 2021). "In addition, extensive evidence indicates that ClpB supports the virulence of numerous bacteria, including pathogenic spirochaete Leptospira interrogans responsible for leptospirosis in animals and humans." (PMID 32932775, 2020). "Importantly, ClpB deficiency made this pathogen avirulent in an animal model of acute leptospirosis (in gerbils) as compared to its parental strain." (PMID 32932775, 2020). "ClpB plays a crucial role not only in the survival of bacteria under stressful conditions, but also in supporting the virulence of some bacterial pathogens, including a pathogenic spirochete Leptospira interrogans responsible for leptospirosis affecting animals and humans worldwide." (PMID 29670056, 2018). "The role and significance of ClpB in leptospiral virulence and pathogenesis of leptospirosis was discussed in detail in a recent review." (PMID 34070174, 2021). "Certainly, further studies are needed to fully resolve the role of ClpB in leptospiral virulence and the pathogenesis of leptospirosis, a zoonotic disease with a significant impact on public health worldwide." (PMID 34070174, 2021). "Further studies are needed to fully explore and understand the role of ClpB in leptospiral virulence and pathogenesis of leptospirosis, a disease that is a common problem for humans and animals throughout the world." (PMID 32932775, 2020). "The role of stress and stress response in the host–pathogen interactions, and also the participation of ClpB in the pathogen’s stress response, designate a new field of research on molecular mechanisms of leptospirosis." (PMID 32932775, 2020). "The aim of this review is to discuss the most important aspects of ClpB’s function in L. interrogans, including contribution of ClpB to leptospiral virulence and pathogenesis of leptospirosis, a zoonotic disease with a significant impact on public health worldwide." (PMID 32932775, 2020). "To further elucidate ClpB’s role in leptospiral virulence and pathogenesis of leptospirosis, we have identified putative substrates for this chaperone, i.e., proteins that may require the assistance of ClpB in L. interrogans cells under stress conditions, including host-induced stress." (PMID 32932775, 2020).
anorexia nervosa (3 papers, 2019 to 2022). A disorder most often seen in adolescent females characterized by a refusal to maintain a minimally normal body weight, an intense fear of gaining weight, a disturbance in body image, and, in postmenarcheal females, the development of amenorrhea. "These abnormally high ClpB concentrations and all associated factors, and therefore might contribute to the initiation and/or perpetuation of anorexia nervosa by interfering with satiety signaling." (PMID 31635300, 2019). "In anorexia nervosa, dysbiosis of Escherichia coli, specifically in the gut microbiome, leads to the secretion of the ClpB protein, which increases the drive for slimness or interpersonal distrust." (PMID 36231182, 2022). "Using the data from this article and others, we can propose anintegrative perspective which links dietary restriction, stress, microbiota-gut-brain axis dysregulation (including increased ClpB signaling) and the on-going self-maintenance of anorexia nervosa." (PMID 31635300, 2019).
tularaemia (2 papers, 2017 to 2020). "Finally, we evaluated the role of ClpB in vivo in a mouse model of tularaemia." (PMID 28621333, 2017).
autosomal dominant severe congenital neutropenia 9 (1 paper, 2022). "More recently, heterozygous missense mutations within the nucleotide-binding domain (NBD) of CLPB have been reported to contribute to autosomal dominant severe congenital neutropenia 9 (SCN9 MIM #619813)." (PMID 36475414, 2022).
bacteremia (1 paper, 2014). "Although peak bacteremia was the same in B6 and TLR2 KO mice (day 3 post-inoculation), LVS clpB clearance was delayed in the spleen, liver, and lung of TLR2 KO mice." (PMID 25250027, 2014).
Brain atrophy (1 paper, 2022). Partial or complete wasting (loss) of brain tissue that was once present. "The most significantly downregulated gene in the VS is CLPB, a mitochondrial chaperone, which has been associated with progressive brain atrophy and with the cellular response to alcohol-induced stress." (PMID 35523767, 2022).
bulimia nervosa (1 paper, 2020). A disorder characterized by recurrent episodes of binge-eating over which the individual feels a lack of control; these episodes of binge-eating are followed by recurrent compensatory behavior to prevent weight gain, usually self-induced vomiting. "In addition, these authors reported increased plasma levels of an antibody anti-ClpB in patients with anorexia nervosa, bulimia, and binge-eating disorder." (PMID 32354351, 2020).
cardiomyopathy (1 paper, 2022). A disease of the heart muscle or myocardium proper. "Several of the disorders associated with cardiomyopathy involve genes important for preprotein processing, such as MIPEP, XPNPEP3, CLPB, and HTRA2." (PMID 35328774, 2022). "Genes important in these processes and that are associated with cardiomyopathy include DNAJC19, MAGMAS, TIMM50, MIPEP, XPNPEP3, HTRA2, CLPB and HSPD1." (PMID 35328774, 2022).
colitis (1 paper, 2021). Inflammation of the colon. "Acute administration of liraglutide to TLR4KO mice during DSS colitis increased the expression of ClpB in cecal contents, consistent with the results in wild-type mice." (PMID 33911125, 2021).
gastroenteritis (1 paper, 2021). An inflammatory disorder that affects the upper and lower gastrointestinal tract. "ClpB also plays a vital role in the survival in chicken of S. typhimurium, a major cause of gastroenteritis globally, since a clpB mutant was found to display reduced survival at 42°C in poultry macrophages and during exposure to hypochloric acid and paraquat." (PMID 33968993, 2021).
Hyperglycemia (1 paper, 2023). An increased concentration of glucose in the blood. "Potential ClpB targets, relevant to its anti-hyperglycemic effect, may include MC4R expressing cholinergic parasympathetic neurons, in which activation by MC ligands attenuates hyperglycemia." (PMID 37445766, 2023).
immune thrombocytopenia (1 paper, 2025). "Patient P73 with CLPB, p.Arg599Cys change, developed MDS at the age of 11, underwent HSCT, and survived, but suffered from post-transplant immune thrombocytopenia." (PMID 41383606, 2025).
malnutrition (1 paper, 2022). Inadequate nutrition resulting from poor diet, malabsorption, or abnormal nutrient distribution. "Malnutrition of gut microbiota seems to cause the increased passage of the CLPB fragments of E. coli from the gut to the blood." (PMID 35893544, 2022).
melanoma (1 paper, 2025). A malignant, usually aggressive tumor composed of atypical, neoplastic melanocytes. "ZDHHC11 and CLPB exhibited inconsistent expression trends between TCGA data and melanoma cells." (PMID 40909968, 2025). "In GSE46517, IFFO1, ANKRD10, CLPB, TCAP, and POLG2 displayed high expression, but the expression levels of CHMP4A, ZDHHC11, and ANKMY1 were low in the melanoma group." (PMID 40909968, 2025).
microcephaly (1 paper, 2019). A congenital or acquired developmental disorder in which the circumference of the head is smaller than normal for the person's age and sex. "Disruption of CLPB is related to human congenital microcephaly and small birth weight." (PMID 32047514, 2019).
Pythiosis (1 paper, 2022). A granulomatous disease caused by the aquatic organism PYTHIUM insidiosum and occurring primarily in horses, cattle, dogs, cats, fishes, and rarely in humans. "The pathogen might adopt some of these pathogenicity mechanisms to the identified chaperones (i.e., HSP70, HSP90, and chaperones ClpB and GroEL) during the pathogenesis of pythiosis." (PMID 35628782, 2022).
infection (29 papers, 2013 to 2025). The state of being infected such as from the introduction of a foreign agent such as serum, vaccine, antigenic substance or organism. "The aim of this review was to underline the potential importance of the molecular chaperone ClpB/Hsp100 in infections caused by the pathogenic spirochaete L. interrogans." (PMID 32932775, 2020). "The molecular chaperone ClpB which belongs to the Hsp100/Clp subfamily of the AAA+ ATPases (ATPases associated with diverse cellular activities) is one of the factors which can enhance bacterial survival in the host during infection." (PMID 34070174, 2021). "The protein encoded by the gene ClpB is not only responsible for the survival of L. interrogans under stressed conditions such as the oxidative and thermal, but also for causing and developing infection within the host." (PMID 30723266, 2019). "It has been postulated that ClpB’s protein disaggregation activity supports the survival of pathogenic bacteria under host-induced stresses (e.g., high temperature and oxidative stress), which allows them to rapidly adapt to the human host and establish infection." (PMID 34070174, 2021). "Numerous studies have revealed that ClpB is also involved in supporting the virulence of some bacterial pathogens, including the pathogenic spirochaete L. interrogans, but However, the specific function of ClpB in bacteria during infection of their hosts is still unexplored." (PMID 32932775, 2020). "Ultimately, through high-throughput screening, small molecule inhibitors targeting ClpB are sought out, and their anti-biofilm efficacy is evaluated in in vivo and in vitro models, laying the foundation for the development of novel anti-infection strategies." (PMID 41425934, 2025). "Studies have shown that a P. gingivalis clpB mutant exhibited decreased invasiveness and virulence in a mouse infection model (Kędzierska-Mieszkowska and Zolkiewski, 2021)." (PMID 41425934, 2025). "It is notable that the ClpB chaperone which is induced in these conditions also plays a role in Salmonella type 6 secretion system effector export and virulence, underlining the putative role that incomplete treatment might play in the preconditioning pathogens for human infection." (PMID 38189954, 2024). "We found that ClpB and DnaK are transcriptionally upregulated in A. phagocytophilum 3–5 days after infection of human HL-60 and tick ISE6 cells, which suggests an essential role of the chaperones in supporting the pathogen’s intracellular life cycle." (PMID 38908470, 2024). "The intracellular tick-borne bacterial pathogen A. phagocytophilum upregulates the production of the chaperones ClpB and DnaK during the infection of mammalian and invertebrate cells." (PMID 38908470, 2024). "Intriguingly, in the case of the ClpB, YrbG, and, YdgA proteoform pairs, the expression of a specific proteoform member was notably strongly favored under infection-relevant (InSPI2) conditions." (PMID 38511928, 2024). "ClpB-mediated activation of the host’s immune response was also found during infections with L. interrogans and F. tularensis." (PMID 34070174, 2021). "During the past few decades, a number of studies revealed the ClpB involvement in the virulence of many bacterial pathogens, but a specific function of ClpB during infection remains to be fully elucidated." (PMID 34070174, 2021). "ClpB and effectors PdpD and PdpC are less important for establishing infection in G. mellonella larvae than in mammalian infection models." (PMID 33875476, 2021). "An average delay in killing of approximately 12 to 24 h was observed for the ΔclpB mutant for all infection doses, suggesting that while ClpB contributes to infection, it is largely dispensable." (PMID 33875476, 2021). "The virulence of Listeria monocytogenes, Salmonella typhimurium and Mycobacterium tuberculosis clpB null mutants was also significantly attenuated in the infection models, as compared to the wild-type and complemented strains." (PMID 34070174, 2021).
infection (continued). "One of the fundamental roles of ClpB is to mediate tolerance to stressful conditions, in particular heat, for a wide range of bacterial species, but if and how ClpB contributes to bacterial survival during infection has been less studied." (PMID 33968993, 2021). "Both ibpA and ibpB are controlled by the σ32 regulon, and their large upregulation during φX174 infection is consistent with the significant increase in RpoH transcription factor σ32 (FC +2.0), along with chaperones ClpB (FC +1.7) and DnaJ (FC +1.9)." (PMID 33975962, 2021). "It has been demonstrated that the Francisella ClpB is essential for the pathogen’s survival under stress conditions and also during infection of the host." (PMID 32275693, 2020). "By contributing to the pathogens’ stress survival, ClpB is involved in a molecular dialogue (cross-talk) between the pathogen and its host during the infection process." (PMID 32932775, 2020). "The lower values for each ∆clpB mutant were highly significant for each of the constructs (P < 0.001), demonstrating that ClpB of both subspecies plays a very important role for efficient T6S during infection." (PMID 30054549, 2018). "It has been demonstrated that the L. interrogans ClpB is essential for the pathogen survival under stress conditions and also during infection of the host." (PMID 28700685, 2017). "Recently, it has been demonstrated that L. interrogans ClpB (ClpBLi) is essential for bacterial survival under stressful conditions and also during infection." (PMID 27421882, 2016). "The only exceptions to this were Frr, FdxA, FbpA, and ClpB, in case of H37Rv whose intracellular levels decreased by 48 hrs post-infection." (PMID 26303024, 2015). "Despite LVS clpB’s attenuation, it elicits a robust T-cell response and previous infection with LVS clpB protects 100% of mice challenged with a lethal dose of LVS." (PMID 25250027, 2014). "We discovered that the clpB expression is high during the pathogen’s replication stage of the infection cycle." (PMID 23667479, 2013). "The transcript of E. chaffeensis ClpB (EhClpB) is strongly upregulated after infection of cultured macrophages and its level remains high during the Ehrlichia replicative stage." (PMID 23667479, 2013). "Similarly, clpB mutants in Listeria monocytogenes, Salmonella typhi, and Mycobacterium tuberculosis displayed significantly reduced virulence in infection models (Kędzierska-Mieszkowska and Zolkiewski, 2021)." (PMID 41425934, 2025). "Interestingly, ClpB was also classified as an important leptospiral protein interacting with human proteins upon infection." (PMID 40507805, 2025). "Additionally, exploration of ClpB’s role across diverse bacterial species or infection models is warranted." (PMID 41425934, 2025). "In addition to promoting stress tolerance, multiple important bacterial pathogens are known to utilize ClpB during infection." (PMID 38750480, 2024). "Furthermore, it has been demonstrated that the P. gingivalis clpB null mutant exhibits low invasiveness and attenuated virulence in a murine model of infection." (PMID 34070174, 2021). "Thus, it has been shown that ClpB is essential for leptospiral survival under various stress conditions and also during infection of mammalian hosts." (PMID 32932775, 2020). "Furthermore, in previous studies, we had shown that L. interrogans ClpB (ClpBLi) is not only synthesized but is also immunogenic during the infection process, further supporting its involvement in Leptospira pathogenicity." (PMID 31847479, 2019). "Our results indicate that ClpB’s importance during infection might be due to its role as a molecular chaperone involved in reactivation of protein aggregates." (PMID 28700685, 2017). "Recently, it has been demonstrated that an AAA+ chaperone ClpB (a member of the Hsp100 family) from L. interrogans (ClpBLi) is not only essential for survival of Leptospira under the thermal and oxidative stresses, but also during infection of a host." (PMID 28700685, 2017).
infection (continued). "Compared to plants grown at normal temperatures, whether susceptible or resistant to the virus, the application of constant heat during infection usually caused an increase in the abundances of HSFA2, HSP90, HSP100/ClpB, HSP70 and BiP (an ER HSP70 resident)." (PMID 26792235, 2016). "In addition, the presence of ClpBLi in the infected hamster kidney tissues demonstrates that the chaperone is produced by pathogen during infection of the host further confirming the involvement of ClpB in the pathogenicity of Leptospira." (PMID 27421882, 2016). "B6 mice clear LVS clpB infection by day 10 post-inoculation." (PMID 25250027, 2014). "To begin investigating the biological role of ClpB during the infection cycle of E. chaffeensis, we produced the recombinant EhClpB in Rosetta BL21(DE3) strain of E. coli., which contains tRNAs for the rare Arg codons found in the EhClpB mRNA (assessed with the graphical codon usage analyzer)." (PMID 23667479, 2013). "In contrast to other mammalian in vivo infection models, even one of the T6SS effectors PdpC, PdpD, or OpiA is sufficient to kill G. mellonella larvae, while sheath recycling by ClpB is dispensable." (PMID 33875476, 2021). "Prior infection (i.e., vaccination) with LVS clpB protects B6 mice during a lethal LVS challenge." (PMID 25250027, 2014). "Despite a robust innate immune response during LVS clpB infection, adaptive immunity is required for bacterial clearance and the frequency of IFN-γ producing CD4+ and CD8+ T-cells is similar in mice inoculated with LVS or LVS clpB." (PMID 25250027, 2014). "Therefore, we hypothesized that during the infection process, GBS encounters heat conditions and is able to overcome heat shock via the heat shock protein ClpB." (PMID 38750480, 2024). "Together, these data indicate that the kinetics and magnitude of the T-cell response in the lung during LVS clpB infection is similar in B6 and TLR2 KO mice suggesting that TLR2 signaling is not required to mount an adaptive immune response to LVS clpB." (PMID 25250027, 2014).
bacterial infections (2 papers, 2021 to 2024). "The aim of this review is to discuss the current understanding of the role of ClpB in selected pathogenic bacteria and its importance during bacterial infections in humans." (PMID 34070174, 2021). "It needs to be determined if protein aggregation is a universal factor that affects the pathogens’ survival in infected hosts and how the disaggregase activity of ClpB supports the various adaptive processes that help establish bacterial infections." (PMID 34070174, 2021). "Since ClpB is not found in human cells, this chaperone emerges as an attractive target for novel antimicrobial therapies in combating bacterial infections." (PMID 34070174, 2021). "The absence of ClpB orthologs in mammals, including humans, makes this chaperone an attractive target in combating bacterial infections." (PMID 34070174, 2021).